GRIFIN (galectin-related inter-fiber protein)
Tractability: No criterion of Open Targets' tractability assessment is met for any kind of drug.
Gene: Protein-coding gene on chromosome 7 (2,474,728 to 2,476,894, reverse strand). Ensembl gene ENSG00000275572.
Gene Ontology:
Molecular function: carbohydrate binding
Genetic constraint (gnomAD): Loss-of-function variants: 21 observed, 14.65 expected, observed/expected ratio (o/e) 1.43, 90% interval 1.01 to 1.89. The synonymous counts are far from expectation, so gnomAD's model fits this gene poorly and the ratio says little. Missense variants: 197 observed, 172.16 expected, observed/expected ratio (o/e) 1.14, 90% interval 1.02 to 1.29. Synonymous variants: 99 observed, 74.71 expected, observed/expected ratio (o/e) 1.33, 90% interval 1.12 to 1.57.
Homologues: Orthologues: guinea pig GRIFIN (82% identical), rat Grifin (78% identical), dog GRIFIN (77% identical), macaque GRIFIN (77% identical), mouse Grifin (77% identical), pig GRIFIN (75% identical), tropical clawed frog GRIFIN (38% identical), zebrafish grifin (35% identical), Caenorhabditis elegans lec-1 (24% identical), Caenorhabditis elegans lec-3 (22% identical), Caenorhabditis elegans F40H6.5 (18% identical), Caenorhabditis elegans lec-6 (18% identical), and 3 more. Paralogues in human: LGALS4 (26% identical), LGALS9 (26% identical), LGALS1 (25% identical), LGALS3 (25% identical), LGALS9B (25% identical), LGALS9C (25% identical), LGALS7 (24% identical), LGALS7B (24% identical), LGALS2 (23% identical), LGALS8 (23% identical), LGALSL (23% identical), CLC (19% identical), and 4 more.
Diseases named in the same sentence as GRIFIN in open-access papers:
GRIFIN is named in the same sentence as 2 diseases in open-access papers, as found by Europe PMC text mining. Sharing a sentence is not in itself a finding about the gene and the disease. The quoted sentences say what the papers report.
cataract (1 paper, 2021). Partial or complete opacity of the crystalline lens of one or both eyes that decreases visual acuity and eventually results in blindness. "Previous studies have indicated that GRIFIN may participate in the regulation of the development of lenses, and as a novel candidate gene in our study, the functions of GRIFIN in the development of subcapsular congenital cataract need further study." (PMID 34946854, 2021).
lymphoma (1 paper, 2015). A malignant (clonal) proliferation of B- lymphocytes or T- lymphocytes which involves the lymph nodes, bone marrow and/or extranodal sites. "Several of the recurrently mutated genes have not previously been implicated in human lymphoma, including NLRP5, NLRP14, and GRIFIN." (PMID 26377837, 2015).